TMPRSS2 (transmembrane serine protease 2)
Diseases named in the same sentence as TMPRSS2 in open-access papers (continued):
Sharing a sentence is not in itself a finding about the gene and the disease.
tumor (continued). "The complete absence of ERG-positive tumor areas in 6q15-deleted tumor foci further suggest that the functional consequences of 6q15 deletions may prevent the development of TMPRSS2:ERG fusions." (PMID 26684029, 2016). "Since the TMPRSS2-ERG fusion is known have a genomic origin, due either to a translocation or to a 3-million-bp genomic deletion between the genes, the presence of both isoforms in the same sample can be explained either by tumor heterogeneity or by alternative splicing." (PMID 21261984, 2011). "Hierarchical clustering of tumour expression profiles across common differentially regulated genes resulted in segregation of TMPRSS2–ERG fusion-positive tumours, suggesting that TMPRSS2–ERG fusion-positive tumours have a distinct molecular metabolism that is replicated in multiple cohorts." (PMID 20068566, 2010). "The mRNA transcripts for the fusion gene TMPRSS2:ERG were detected in two out of the four patients who had a high Gleason score and PSA levels, and not in the two low-risk tumours (patient 3 and 4), whereas PCA-3 transcripts were detected in all of the patients after mild prostate massage." (PMID 19401683, 2009). "Thus, promoter methylation of TMPRSS2 may not be the molecular mechanism for TMPRSS2 overexpression in PRAD tumours and PRAD's pathogenesis." (PMID 33609069, 2021). "However, in the six aNEC patients with an unknown primary tumor, no molecular clues, such as TMPRSS2-ERG fusions were found pointing to a specific tissue of origin." (PMID 34326338, 2021). "For this reason, the primary objectives were to grow tumor cells in 2D and 3D tissue culture systems and to determine whether the cells grown in the culture systems and primary tumor cells had the same features of methylation in the genes PAX5, TMPRSS2, and SBDS." (PMID 30792990, 2019). "The ERG−/PTEN+ tumour molecular subtype of PCa is described by the absence of ERG rearrangements, such as TMPRSS2:ERG fusions, and the retention of PTEN function, which is important for controlling the PI3K/AKT signalling pathway." (PMID 40165885, 2025). "In the ex vivo analysis of the VCaP tumor samples for effects on the AR signaling pathway, we found a significant reduction of FKBP5 and TMPRSS2 expression after enzalutamide treatment, but no significant changes were seen in the BAY-155 treated study arm." (PMID 31947537, 2020). "Here we provide additional evidence suggesting that tumor tissues are less prone to SARS-CoV-2 infection than non-tumorous tissues, due to reduced expression of TMPRSS2." (PMID 32967703, 2020). "The absence of statistical relationship to TMPRSS2:ERG fusion status, chromosomal deletion or high tumor cell proliferation argues against a major role of PSCA for regulation of cell cycle or genomic integrity." (PMID 29855276, 2018). "Deletions in MAP3K7 have recently been associated with early PSA recurrence, and in tumours that do not contain the TMPRSS2-ERG gene fusion, a tumour-suppressor role for MAP3K7 has been proposed." (PMID 26501111, 2015). "ETV4 is involved in translocations with TMPRSS2 in PCa less often, and, as seen in a GEMM, while ETV4 expression appears not to affect tumor growth per se, it induces metastatic progression in cooperation with activated PI3K pathway." (PMID 25277175, 2014). "In our analysis, the androgen regulated genes enriched in tumor with no deletion of PTEN include genes expressed in normal prostate luminal epithelium such as KLK3 (PSA), TMPRSS2, and NKX3-1." (PMID 23171135, 2012). "Additionally, the absence of matched tumour genomic data, such as TMPRSS2-ERG fusion status, although reportedly less frequent in southern African-derived tumours, precluded relevant adjustments." (PMID 41057544, 2025). "Interestingly, in multivariate logistic regression analyses, only TMPRSS2:ERG added significant predictive value to the ERSPC-RC to predict biopsy Gleason score (OR, 7.16; P < 0.001) and clinical tumor stage (OR, 2.60; P = 0.023), whereas PCA3 did not." (PMID 26339615, 2015).
tumor (continued). "Thus, plasma-Seq identified multiple rearrangements, that is, the TMPRSS2-ERG deletion on chromosome 21, which had not been present in the primary tumor." (PMID 23561577, 2013). "While it is not frequently reported in normal prostate tissue, TMPRSS2:ERG fusions facilitate tumour progression by promoting angiogenesis, inflammation, and epithelial–mesenchymal transition ultimately leading to metastasis, advanced tumour stages, and increased mortality." (PMID 40165885, 2025).
adenocarcinoma (22 papers, 2011 to 2025). A common cancer characterized by the presence of malignant glandular cells. "This suggests that the TMPRSS2:ERG fusion gene is an early event but associated with progression from HGPIN to adenocarcinoma." (PMID 33634124, 2021). "This action caused a significant decline in SARS-CoV-2 replication in A549ACE2/TMPRSS2 cells (adenocarcinoma human alveolar basal epithelial cells overexpressing ACE2 and TMPRSS2) and in primary human airway epithelial cells (HAE)." (PMID 41229690, 2025). "In all NSAID-fed groups, compared to no-drug controls, there was a significant decrease in higher-grade adenocarcinoma incidence in the TMPRSS2-ERG (fusion)-driven PCa model." (PMID 37894421, 2023). "According to a study in androgen-sensitive human prostate (LNCaP) adenocarcinoma cells, kaempferol (flavonol) suppressed TMPRSS2 by 49.14% and 79.48% at 5 and 15 μM, respectively." (PMID 34207756, 2021). "Another study showed that the terpene class cryptotanshinone isolated from Salvia miltiorrhiza effectively exhibited anti-TMPRSS2 activity at 0.5 μM in the androgen-sensitive human prostate (LNCaP) adenocarcinoma cell line." (PMID 34207756, 2021). "Finally, but not for importance, there is the ability of the extract to downregulate the gene expression of ACE2 and TMPRSS2 in human adenocarcinoma H1299 cells." (PMID 34361576, 2021). "The number of fusion reads is generally lower than that of the TMPRSS2 transcript (adenocarcinoma NGS data SRX027125) and may be an indicator of lower expression of the fusion, and/or cellular mosaicism." (PMID 21589938, 2011). "One of the adenocarcinomas, T1, is ETS-negative, and the remaining adenocarcinomas are ETS-positive, with the positive expression of an ETS family member conferred by a TMPRSS2-ERG gene fusion." (PMID 21261984, 2011). "In both experiments, we found the fusion in 2/3 adenocarcinoma samples (SRX027124, SRX027125) and 1/3 adjacent normal sample (SRX027128) with reads spanning the fusion coordinate and containing both unique ERG and TMPRSS2 bases." (PMID 21589938, 2011).
prostate (14 papers, 2012 to 2025). "A gene named transmembrane serine protease 2 (TMPRSS2) for which alteration was historically associated with prostate tumorigenesis was recently confirmed to be involved in facilitating the SARS-CoV-2 entry into host cells." (PMID 33472649, 2021). "TMPRSS2, another component of these typical androgen-regulated PCa translocations, is highly expressed in PCa cells, contributing to prostate tumorigenesis." (PMID 23130941, 2012). "In the specific case of TMPRSS2-ERG, the androgen sensitivity of the TMPRSS2 promoter is responsible for the steroid-dependent expression of oncogene ERG in prostate epithelium, a key event in prostate carcinogenesis." (PMID 27285981, 2016). "The failure of the TMPRSS2–ERG fusion to stratify PCa cases into early and late stages may be because the fusion is an early clonal event in prostate carcinogenesis." (PMID 37239316, 2023).
infectious disease (8 papers, 2021 to 2025). A disorder directly resulting from the presence and activity of a microbial, viral, or parasitic agent in humans. "The expression pattern and the role of TMPRSS2 in several infectious diseases render significant level of safety in assuming that the protease has a major role in cellular entry of SARS-CoV-2 in human cells." (PMID 34336361, 2021). "In the complex infectious disease case of SARS-CoV-2, mediKanren unveiled the pathway of androgen-induced expression of TMPRSS2, which ultimately led to a clinical trial of androgen deprivation therapy for decreasing disease severity." (PMID 36248623, 2022).
respiratory diseases (8 papers, 2020 to 2025). "As such, α1AT was identified as inhibitor of pathogens causing respiratory diseases where the mechanism of inhibition involves direct interaction of either TMPRSS2 or PT with α1AT, different amino acid residues of α1AT seem to be responsible for driving the interaction." (PMID 39481600, 2024). "Given that common AT2 variants showed predicted regulatory function and association with respiratory disease, we next asked whether these variants regulated the expression of TMPRSS2 using human lung eQTL (expression quantitative trait loci) data from the GTEx v8 release." (PMID 33164753, 2020). "Furthermore, targeting TMPRSS2 may apply to other respiratory diseases besides SARS-CoV-2, such as other influenza viruses." (PMID 40297833, 2025).
cardiovascular disease (5 papers, 2021 to 2024). "TMPRSS2 is abundantly found in the endothelium of coronary arteries and pericytes of intramyocardial microvessels, and TMPRSS2 inhibitors are being studied as a potential treatment for cardiovascular disease by reducing atherothrombosis and inflammation." (PMID 39511582, 2024). "We sought to analyze the impact of sex hormones, age, and cardiovascular disease on ACE-2 and TMPRSS-2 expression in different mouse models." (PMID 34907257, 2021).
gastrointestinal tumor (2 papers, 2021 to 2022). "As TMPRSS2 and TMPRSS4 gene expression is positively correlated in both GI tumors and cell lines, we initially investigated whether there is an additional number of genes which are commonly associated with TMPRSS2 and TMPRSS4 genes in GI cancer cell lines." (PMID 35970857, 2022). "Importantly, all gastrointestinal tumor samples showed a positive correlation between TMPRSS2 and TMPRSS4 genes." (PMID 35970857, 2022). "Given that the co-expression analysis with TMPRSS2-TMPRSS4 resulted in a positive correlation with TRIM31 in all GI samples, we further investigated the functional role of TRIM31 in GI tumors." (PMID 35970857, 2022). "We therefore characterized the expression profiles of a number of genes involved in SARS-CoV-2 infection pathway and found higher ACE2, TMPRSS2, TMPRSS4, SCARB1, CTSL and NRP1 expression in all GI tumor samples relative to their normal counterparts." (PMID 35970857, 2022). "There was also significant positive correlation of TRIM31 with TMPRSS2 and TMPRSS4 gene pair in all GI tumor samples." (PMID 35970857, 2022). "Among these, TMPRSS2 and TMPRSS4 was commonly observed in all gastrointestinal tumor types." (PMID 35970857, 2022).
heart disease (2 papers, 2022 to 2024). "Several relevant trials have delved into how sex hormones affect multiple facets of COVID‐19, including their role in the regulation of ACE2 and TMPRSS2, immune reactions, and the risk of developing complications such as heart disease." (PMID 38923119, 2024).
neurologic disorders (2 papers, 2021 to 2022). "Indeed, identified genes are implicated in viral (SEC14L1, JMJD6, SRSF2, TMPRSS2, MX1, MX2) bacterial (COL8A1, SPIRE1), and neurological disorders (MFSD11, METTL23, CTTNBP2, BACE2, IMPA2, MPPE1 and GNAL), or in the functions of the Golgi complex (MGAT5B), organelle where viral envelope is occurred." (PMID 35581286, 2022).
bacterial infection (1 paper, 2023). "Overall, our data suggest that TMPRSS2 expression in airway cells is elevated upon bacterial infection." (PMID 37208193, 2023). "Our data suggest that TMPRSS2 might play a role in innate host response of airway cells to bacterial infections." (PMID 37208193, 2023).
gastro-intestinal disorders (1 paper, 2022). "We only observed that the G allele of the TMPRSS2 rs2070788 was associated with higher development of post-COVID dyspnea and gastro-intestinal disorders (both, p < 0.01)." (PMID 36360172, 2022).
neurodegenerative disease (1 paper, 2023). A disorder of the central nervous system characterized by gradual and progressive loss of neural tissue and neurologic function. "Recent studies exhibited that hypothalamic miRNAs including miR-548C-3p are potential contributors to different neurodegenerative diseases, also this author identified 29 novel hypothalamic MicroRNAs as a propitious therapeutic regimen for SARS-CoV-2 by regulating ACE2 and TMPRSS2 expression." (PMID 37359008, 2023).
TMPRSS2 also shares sentences with these, for which no sentence is quoted: rectal adenocarcinoma (7 papers); colon adenocarcinoma (5); endometrial carcinoma (5); idiopathic pulmonary fibrosis (5); stomach adenocarcinoma (5); uterine corpus endometrial carcinoma (5); viral diseases (5); androgenetic alopecia (4); lung squamous cell carcinoma (4); reflux esophagitis (4); atherosclerosis (3); cervical squamous cell carcinoma (3); colorectal tumor (3); esophageal squamous cell carcinoma (3); hyperlipidaemia (3); acute respiratory distress syndrome (2); Ageusia (2); allergic rhinitis (2); cholangiocarcinoma (2); chronic kidney disease (2); chronic lymphocytic leukemia (2); depression (2); endocervical adenocarcinoma (2); Epiphora (2); glomerulosclerosis (2); hypogonadism (2); immune dysfunction (2); Insulin resistance (2); interstitial lung disease (2); intestinal infection (2).
A further 117 diseases each share a sentence with TMPRSS2 in 2 papers or fewer.